AR (androgen receptor)
Diseases named in the same sentence as AR in open-access papers (continued):
Sharing a sentence is not in itself a finding about the gene and the disease.
prostate carcinoma (continued). "Aberrant activation of androgen and AR-mediated signaling pathways also directly contributes to the pathogenesis of prostate cancer (PCa)." (PMID 39369165, 2024). "On the other hand, overexpression of AR can potentiate Wnt/β-catenin signaling in prostate cancer cells under castrate levels of androgen and activated Wnt signaling can recruit AR to the promoters of Wnt target genes." (PMID 38531859, 2024). "HOTAIR is also involved in regulating proliferating renal cell carcinomas and can control the transcription of androgen receptor targets, contributing to a more resistant response to antiandrogens in prostate cancer." (PMID 38095719, 2024). "The overexpression of AhR was shown to enhance Src kinase activity, further promoting AR signaling and prostate cancer progression." (PMID 39184676, 2024). "In this study, the interaction of serum nucleases with the mentioned SNA-siRNA-AR was analyzed based on the capacity of knocking down human androgen receptor (AR) expression in lymph node carcinoma of the prostate (LNCaP) for prostate cancer (PC) therapy." (PMID 38951806, 2024). "With this oncogenic activation, it promotes cancer stemness, activated stroma and altered microenvironment, EMT and metastasis, reciprocal crosstalk with androgen receptor (AR) and therapy-resistance in different stages of prostate cancer progression." (PMID 38531859, 2024). "This phenomenon is not restricted to the AR-negative subtype, as GR can induce FOXO3 and GAS5 expression in AR-positive prostate cancer cells as well." (PMID 39027480, 2024). "More impressively, assessment of CBPD-409’s cytotoxicity in a large panel of 131 normal and cancer cell lines from 22 distinct lineages found AR-positive prostate cancer cells to be amongst the most sensitive models." (PMID 38586029, 2024). "For instance, ZNF451 positively regulates androgen signaling in prostate cancer cells by acting as a transcriptional coactivator for the androgen receptor." (PMID 38600524, 2024). "Targeting heterogeneous tumor populations in advanced prostate cancer is crucial, as these tumors often have some cells retaining AR dependence and others developing AR-independent resistance mechanisms." (PMID 39200727, 2024). "Curcumin induces autophagy in both AR-positive and AR-negative prostate cancer cells by reducing the activity and expression of the androgen receptor (AR) and related cofactors AP-1, NF-κB, and CBP." (PMID 39770516, 2024). "Transcriptomic and epigenomic approaches revealed that CDKI-73 suppressed signaling pathways regulated by AR, MYC, and BRD4, key drivers of dysregulated transcription in prostate cancer, and reprogrammed cancer-associated super-enhancers." (PMID 39117800, 2024). "The incidence rates of both NEPC and DNPC have notably increased following the introduction of second-line antiandrogens into the drug regimen of patients, and NEPC and DNPC exhibit worse survival outcomes compared to AR-positive prostate cancer." (PMID 39027480, 2024). "The androgen receptor signaling pathway has been identified as the primary driving force in the development and progression of lethal castration-resistant prostate cancer." (PMID 38339414, 2024). "This study evaluated the effects of docetaxel and androgen receptor signaling inhibitors as second-line treatments in patients with castration-resistant prostate cancer after androgen receptor signaling inhibitors as first-line treatment." (PMID 39135744, 2024). "Being a hormone-dependent tumor, prostate cancer requires the androgen and androgen receptor (AR) signal axis to maintain normal function." (PMID 38384328, 2024). "Overall, pSHP2/pY54-H3 signaling acts as a sentinel of AR homeostasis, explaining not only growth retardation, genital abnormalities and infertility among NSML patients, but also significant AR upregulation in prostate cancer patients." (PMID 38965223, 2024).
prostate carcinoma (continued). "The anticancer properties of hinokitiol have been confirmed, among others, in relation to prostate cancer, where Liu and Yamauchi found disruption of androgen receptor signaling." (PMID 38675392, 2024). "The expression of retinoic-acid-receptor-related orphan receptor (RORγ) is significantly upregulated in prostate cancer, which subsequently drives the expression of the androgen receptor (AR)." (PMID 39771106, 2024). "Androgens, such as dihydrotestosterone (DHT) acting through the androgen receptor (AR), play a critical role in the development and growth of prostate cancer by promoting cell proliferation in the prostate." (PMID 38731981, 2024). "Recent evidence has highlighted the crosstalk between the glucocorticoid receptor (GR) and AR, demonstrating that GR can induce prostate cancer therapy resistance by replacing the inactivated AR, thereby becoming a driver of the disease." (PMID 39027480, 2024). "Almost all primary prostate cancer (PCa) cells express the AR and depend on androgens for their oncogenic growth." (PMID 38336745, 2024). "AR degraders were then evaluated for their AR degradation potential by treating the prostate cancer cell line VCaP with 0.01, 0.1, 1, or 10 μm of each compound for 20 h and monitoring the AR protein levels." (PMID 38958553, 2024). "In this study, we examined the chromatin landscape of AR-positive prostate cancer cells post-exposure to the AR inhibitor enzalutamide." (PMID 38554106, 2024). "Now that many prostate cancer (PCa) patients are treated upfront with AR-targeted agents, it is critical to identify actionable mechanisms that drive phenotypic plasticity, to prevent the emergence of resistance." (PMID 39560993, 2024). "Apart from AR and ER, GR-mediated signaling pathways are emerging as key players in breast and prostate cancers." (PMID 39199690, 2024). "The current study reveals the synthesis of new pyrazolylmethylene-2-thioxoimidazolidin-4-one derivatives as anti-prostate-cancer agents via targeting the androgen receptor." (PMID 39062524, 2024). "hCCAR2 is a coactivator of the androgen receptor (AR-V7 variant) and its downstream targets, such as CDH2, to increase the growth of prostate cancer cells." (PMID 38172598, 2024). "Prospective circulating tumor DNA and germline DNA analysis was performed in patients with metastatic castration-resistant prostate cancer before randomization to androgen receptor pathway inhibitors (ARPIs), taxanes or a physician’s choice control arm." (PMID 39164518, 2024). "SCD: SCD is upregulated in many cancers, including androgen receptor (AR)+ LNCaP prostate cancer cells, ErbB2-driven breast cancer cells, pancreatic cancer cells, glioblastoma cells, non-small-cell lung cancer patient samples (NSCLC), and gastric cancer cells." (PMID 38610991, 2024). "This dual role of AhR is highlighted in studies where its overexpression enhances Src kinase activity, thereby promoting AR signaling and prostate cancer progression." (PMID 39184676, 2024). "Standard of care treatments for patients with advanced prostate cancer include therapies that inhibit the androgen receptor (AR), a transcription factor essential for the homeostasis and survival of prostate cancer cells." (PMID 39663356, 2024). "SAFB1 has a role in prostate cancer, regulating AR as a co-repressor through the epigenic silencing of AR targets, such as PSA." (PMID 39000020, 2024). "The CRPC phenotypes include androgen receptor–active prostate cancer (ARPC) and neuroendocrine prostate cancer (NEPC)." (PMID 39485722, 2024). "Dysregulation of transcription factors has been associated with the development of lineage plasticity, leading to the transformation of prostate cancer into AR-independent prostate cancer with neuroendocrine features." (PMID 38698344, 2024). "Based on SKP1-CUL1-F-box, scientists have applied PROTAC to achieve targeted degradation of breast cancer-related estrogen receptor (ER) and prostate cancer-related androgen receptor (AR)." (PMID 38664743, 2024).
prostate carcinoma (continued). "The AR signaling pathway plays an essential role in prostate cancer, and significant differences in AR activity have been documented between AA and Caucasian men." (PMID 39600743, 2024). "Elevated levels of monoacylglycerol lipase (MAGL) in AR-independent prostate cancer contribute to malignancy through endocannabinoid and fatty acid pathways." (PMID 38969865, 2024). "Androgen receptor (AR)-mediated transcription plays a critical role in development and prostate cancer growth." (PMID 39489778, 2024). "The androgen receptor serves as the principal pharmacological target in the treatment of prostate cancer." (PMID 39772046, 2024). "Although PC-3 cancer cells are also androgen-independent prostate cancer cells, they lack AR, and their growth is completely unaffected by androgen." (PMID 38731782, 2024). "Some of the genes that have been linked to the development of prostate cancer are PIK3R1, SRC, STAT3, HSP90AA1, AKT1, MAPK1, SESR1, and AR." (PMID 39114070, 2024). "Taken together, these findings provide evidence that WAM induces apoptosis via the inhibition of HSP27/AR signaling in prostate cancer cells and is a potent anticancer candidate for prostate cancer treatment." (PMID 38474045, 2024). "Central to this investigation are the AHR and AR signaling pathways, which play crucial roles in the progression and severity of prostate cancer." (PMID 39600743, 2024). "In this paper, we present the first evidence of an association between AR (CAG)n and APEX1 c.444T>G polymorphisms and the risk of biochemical recurrence in Argentine patients with prostate cancer (PCa)." (PMID 39594771, 2024). "In conclusion, our study highlights the involvement of MED12 and CDK8/19 in c-Myc, AR activity, and cell response to enzalutamide in prostate cancer." (PMID 39253786, 2024). "For decades, effective prostate cancer treatments have disrupted the androgen receptor (AR) signaling pathway through androgen deprivation therapies (ADTs)." (PMID 39591176, 2024). "PROTACs have also been shown to be effective in reversing resistance in prostate cancer to androgen receptor (AR) antagonists." (PMID 39200265, 2024). "Their antiproliferative potency (IC50 values) against AR-positive prostate cancer cells, along with the degradability of representative androgen receptor PROTACs, have been summarized." (PMID 38339414, 2024). "XY018 and SR2211, which are RORγ-selective antagonists, were found to inhibit the proliferation of prostate cancer cells expressing the androgen receptor." (PMID 39012661, 2024). "IL-6 facilitates the transition from hormone-dependent to castration-resistant prostate cancer by activating androgen receptor signaling." (PMID 39125867, 2024). "Previous studies have demonstrated that AR inhibition with agents such as darolutamide results in the downregulation of DNA damage repair (DDR) genes in prostate cancer." (PMID 39769434, 2024). "Exposure to high BPA doses separates androgen-mediated transcription from AR-mediated mitogenesis in prostate carcinoma cells." (PMID 39596429, 2024). "Many studies have demonstrated the AR function in PCa progression, including the Castration-Resistant Prostate Cancer phenotype (CRPC)." (PMID 38305916, 2024). "CPA mediates the hyperphosphorylation of HNRNP K in vivo and increases the tight binding of HNRNP K to androgen receptor (AR), which is often used in the clinical treatment of advanced prostate cancer." (PMID 39366930, 2024). "Somatic mutations in the AR gene have been found to be particularly prevalent in CRPC, where its somatic mutation rate is about 16.8% (72/429) based on data from 429 prostate cancer patients in the Cancer Genome Atlas (TCGA) database." (PMID 38182647, 2024). "Prostate cancer progression is controlled by androgen receptor signaling and angiogenesis, which promote metastatic prostate cancer growth." (PMID 38792519, 2024).
prostate carcinoma (continued). "UBX‐390 suppresses chromatin binding and gene expression of AR and demonstrates substantial efficacy in the degradation of AR mutants in patients with treatment‐resistant prostate cancer." (PMID 38958553, 2024). "Berberine inhibits prostate cancer cell proliferation and reduces the expression of AR, prostate-specific antigen (PSA), COX-2, and B-cell leukemia/lymphoma 2 (Bcl-2)." (PMID 39062777, 2024). "Camptothecin, a DNA topoisomerase 1 inhibitor that disrupts the HSP90-AR complex, inhibits AR transcriptional activity and suppresses prostate cancer cell growth." (PMID 38339390, 2024). "In HSPC prostate cancer cells, AR acts as a licensing factor for DNA replication, requiring degradation during each cell cycle to enable DNA replication in the subsequent cycle." (PMID 38201308, 2024). "Flavonoids have demonstrated high affinity toward the androgen receptor (AR) in human prostate cancer cell lines through the AR-dependent signaling pathway by decreasing the secretion of prostate-specific antigen levels and heat shock proteins." (PMID 39057691, 2024). "In vivo, CPA mediates AKT hyperphosphorylation of HNRNP K at Ser116 and increases its tight binding to androgen receptor (AR), which delays prostate cancer progression." (PMID 39366930, 2024). "Enzalutamide is a second-generation androgen receptor antagonist that is used to treat castrate-resistant prostate cancer." (PMID 39272811, 2024). "Androgen receptor (AR) antagonists are widely used for the treatment of prostate cancer (PCa), but their therapeutic efficacy is usually compromised by the rapid emergence of drug resistance." (PMID 38481034, 2024). "Altogether, these findings suggest that degradation of p300/CBP rapidly depletes active histone acetylation marks at AR enhancers in prostate cancer cells." (PMID 38586029, 2024). "Studies in transgenic mouse models show that Wnt-5a can act as an activator of AR-mediated prostate cancer growth and Wnt-5a-mediated activation of β-catenin signaling can cooperate with Pten loss to drive AR-independent CRPC." (PMID 38531859, 2024). "In prostate cancer, the AR signaling pathway is often upregulated, leading to uncontrolled cell proliferation." (PMID 39184676, 2024). "The findings suggest that patients with certain alleles (AR (CAG)M and the heterozygous APEX1 c.444TG genotype) are linked to an increased risk of prostate cancer relapse, even when accounting for conventional clinicopathological variables." (PMID 39594771, 2024). "On molecular level, we demonstrated that DPYSL5 expression is under AR regulation, and the NE phenotype is inducible with the clinically used second -generation AR inhibitor Enzalutamide (ENZ) in prostate cancer cells." (PMID 38238517, 2024). "This selective approach offers enhanced therapeutic efficacy with reduced off-target effects, particularly in cancer types like acute myeloid leukemia (AML) and prostate cancer that express the androgen receptor (AR)." (PMID 39066258, 2024). "ICA has demonstrated anti-proliferative effects on prostate cancer cells by modulating the androgen receptor signaling pathway." (PMID 39759453, 2024). "A study illustrated that AhR overexpression enhances Src kinase activity, which in turn promotes AR signaling and prostate cancer progression." (PMID 39184676, 2024). "SDC, like prostate cancer (PCa), relies on the androgen receptor (AR) signalling pathway for tumour growth, and therefore androgen-receptor signalling inhibitors (ARSI) and androgen deprivation therapy (ADT) have been studied." (PMID 39304797, 2024). "In this study, we verify that earlier finding by using either siRNA depletion or an MDM2i, both of which led to enhanced AR protein levels in prostate cancer cells." (PMID 38410785, 2024). "While miR-21 downregulates AR leading to a deleterious effect on cardiac fibrosis, in prostate cancer, miR-21 increases AR protein expression and is involved in tumor pathogenesis." (PMID 38987854, 2024).
prostate carcinoma (continued). "It directly interacts with AR and is critical for AR recruitment to enhancer sites in prostate cancer." (PMID 38391963, 2024). "Targeting these factors can significantly impact the treatment of specific malignancies, as exemplified by the clinical success of agents targeting the androgen receptor (AR) in prostate cancer and estrogen receptor (ER) in breast cancer." (PMID 38328238, 2024). "Collectively, our work demonstrates that CDKI-73 has activity in a diverse array of aggressive prostate cancer subtypes, including AR-driven and AR-independent disease." (PMID 39117800, 2024). "Contradictory to its role in AR-positive prostate cancer, filamin A cleavage by calpain augments tumour cell metastasis in a calcium-dependent manner." (PMID 38958472, 2024). "PROX1 expression positively correlated with neuroendocrine score and negatively correlated with AR score in prostate cancer patient data sets." (PMID 39470735, 2024). "For instance, the cross-talk between PI3K and androgen receptor (AR) signaling pathways promotes pathogenesis and treatment resistance in prostate cancer." (PMID 39507514, 2024). "Clinically, outside of prostate cancer treatments, anti-androgens (AR antagonists) are extensively used in males for the treatment of benign prostate hyperplasia, androgenic alopecia, hypersexuality, paraphilias and precociously puberty." (PMID 38750183, 2024). "Central to the management of prostate cancer is the targeting of the androgen receptor signaling pathway, which plays a pivotal role in driving prostate cancer cell proliferation and growth." (PMID 39195294, 2024). "Previous studies have shown that ING3 promotes prostate cancer growth by activating the androgen receptor, and PHF20 promotes glioblastoma cell malignancies through a WISP1/BGN‐Dependent pathway." (PMID 39538416, 2024). "HypoDMRs in prostate tumors of EA men were enriched for previously known prostate cancer-associated transcription factors, including FOXA1 and AR." (PMID 38566104, 2024). "Consistently, in CRISPR-based dependency maps (DepMap), p300 ranks as the most essential histone acetyltransferase in AR-driven prostate cancer cells, implying a pivotal role of p300/H2BNTac on prostate cancer cell viability." (PMID 38586029, 2024). "Research in prostate cancer (PCa) cell lines has previously demonstrated a PI3K-independent suppression of AR mRNA after EGF ligand treatment and a PI3K-dependent mechanism for AR degradation after HRG treatment." (PMID 38339304, 2024). "Instead, alternative treatments like androgen receptor blockade, stimulation, or immunotherapy should be considered and have been suggested for breast cancer and AR-responsive prostate cancer patients." (PMID 39684829, 2024). "N-Myc is capable of suppressing AR-signaling and driving lineage plasticity, tumor aggressiveness, and AR-independent progression in prostate cancer preclinical models." (PMID 39103353, 2024). "Given that the generation of AR-Vs is prostate cancer’s evolutionary adaptive response to ADT, it is strategic to attack prostate cancer’s Achilles’ heel from different angles with indirect targeting agents." (PMID 38201308, 2024). "While AR-targeted therapies form the cornerstone of prostate cancer treatment, they often inadvertently activate compensatory pathways, leading to therapy resistance." (PMID 39027480, 2024). "These prostate cancer subtypes are typically refractory to AR-directed therapies and exhibit poor clinical outcomes." (PMID 38667288, 2024). "In a biomarker-driven, outcome-adaptive platform trial for patients with metastatic castration-resistant prostate cancer, androgen receptor pathway inhibitors showed longer survival with respect to taxanes and physician’s choice treatment." (PMID 39164518, 2024). "Regarding ETS family proteins, ERG is known to modulate the chromatin binding of AR in prostate cancer cells." (PMID 39027480, 2024).